INS (insulin)
Diseases named in the same sentence as INS in open-access papers (continued):
Sharing a sentence is not in itself a finding about the gene and the disease.
Insulin resistance (continued). "In mice, chronic LPS infusion perturbed glucose tolerance by inducing hepatic insulin resistance and hampering glucose-stimulated insulin secretion." (PMID 33178196, 2020). "Male mice demonstrated significantly higher fasting glucose compared to OBC, whereas female mice demonstrated significantly higher insulin levels and markers of insulin resistance compared to OBC." (PMID 32545529, 2020). "Significant increases in fasting glucose, fasting insulin, insulin resistance index, triglyceride, cholesterol, and LDL-C and decreases in HDL-C were observed at 12 weeks." (PMID 32528286, 2020). "In females, glucose AUC, fasting insulin and Homeostatic model assessment of insulin resistance (HOMA-IR) in the OBC group were significantly lower than in the CON group (p < 0.05)." (PMID 32545529, 2020). "At hepatic level, insulin resistance increases glucose production is due to an impaired ability of insulin to suppress the activity of gluconeogenic enzymes." (PMID 32580324, 2020). "Insulin resistance (IR) has been defined as a dysmetabolic condition in which the peptide hormone insulin produces a less-than-expected biological effect on peripheral target tissues, leading to hyperinsulinemia, the diagnostic hallmark of IR." (PMID 32290535, 2020). "Type 2 diabetes is the most common type of diabetes mellitus and characterized by insulin resistance and relatively reduced insulin secretion." (PMID 32967670, 2020). "HOMA-insulin resistance (IR) was estimated as the product of fasting glucose (mmol/l) and insulin (μU/ml) divided by the constant 22.5, with values ≥ 2.6 denoting IR15." (PMID 32873820, 2020). "In some in vitro studies, FAP-derived adipocytes are actually more insulin resistant than other adipocytes, possibly relating increased myosteatosis with insulin resistance and making this a very active area of investigation." (PMID 32903666, 2020). "Furthermore, intravenous glucose and insulin tolerance tests, paired with the corresponding values associated with the area under the curve, demonstrated that kaempferol led to less severe impairment of glucose tolerance and insulin resistance in the HFD+kaempferol group than in the HFD group." (PMID 32337249, 2020). "The general concept for the involvement of p38 MAPK in insulin resistance is that its activity inhibits insulin signaling by enhancing inhibitory phosphorylation of IRS1 at Ser307 and other related residues." (PMID 32899870, 2020). "The roles of NR4As in insulin secretion and insulin resistance were also different in different cell lines and mice models used for research." (PMID 33328994, 2020). "Both fasting insulin and insulin resistance had decreased significantly by 13.6% and 13.7%, respectively." (PMID 33259020, 2020). "Studies indicate that chronically elevated levels of insulin lead to skeletal muscle insulin resistance by deregulating steps within the insulin signaling cascade." (PMID 32230718, 2020). "For instance, both TNFα and IL-6 induce insulin resistance in rodents and block insulin action in murine (3T3-L1) adipocytes." (PMID 32397353, 2020). "In the insulin-resistant human hepatoma HepG2 cells, compound 25 with the moderate PTP1B inhibition and preferable pharmaceutical properties can significantly increase insulin-stimulated glucose uptake and showed the insulin resistance ameliorating effect." (PMID 31742469, 2020). "Gestational diabetes is glucose intolerance resulted from insufficient insulin supply relative to the degree of insulin resistance in pregnancy." (PMID 32180760, 2020). "Adipose tissue is a key organ that responds to insulin actions and itself can contribute to aggravate insulin resistance." (PMID 32718202, 2020). "The results showed that the levels of glucose, insulin, and insulin resistance index (HOMA-IR) were increased in the model group compared with the control group, which means the animal model of insulin resistance was built successfully." (PMID 32425786, 2020).
Insulin resistance (continued). "Type 2 DM is characterized by insufficient insulin production as well as insulin resistance with the body unable to effectively use the insulin it produces." (PMID 33553047, 2020). "Fasting glucose and insulin were used to calculate the homeostatic model assessment of insulin resistance (HOMA-IR) and body fat percentage was determined via dual energy x-ray absorptiometry." (PMID 32357490, 2020). "Systemic insulin sensitivity was determined by serum glucose and insulin levels and by the homeostasis model assessment of insulin resistance (HOMA-IR)." (PMID 32316103, 2020). "Several markers of obesity and inflammation, including CRP (marker of inflammation), insulin (marker of insulin resistance), and leptin (marker of adiposity) were measured to evaluate their potential associations with estradiol or estrone levels." (PMID 32566743, 2020). "Knockdown of TRIB3 in skeletal muscle improved insulin sensitivity in a rat model for insulin resistance; however, rats exposed to short‐term exercise training improved glucose tolerance without changes in skeletal muscle TRIB3 protein." (PMID 32562350, 2020). "Although fasting glucose levels were unchanged following 12 weeks of treatment, fasting insulin levels decreased, as did the homeostatic model assessment of insulin resistance (HOMA‐IR)." (PMID 32514450, 2020). "Mice and rats made obese by HFD-feeding have been widely used in experimental studies to investigate insulin signaling and insulin resistance at the molecular level." (PMID 32455838, 2020). "After an eight-week intervention, body mass index, waist circumference, fasting glucose, fasting insulin, and homeostatic model assessment for insulin resistance were significantly improved." (PMID 32466456, 2020). "Therapeutic interventions in both animal and human studies have clearly shown this link; improving endothelial function ameliorates insulin resistance, whereas improving insulin sensitivity ameliorates endothelial dysfunction." (PMID 32235782, 2020). "Many recent studies confirm that the endothelium is the target organ of insulin; under conditions of insulin resistance, the microvascular activity of insulin is disturbed, which significantly contributes to the development of cardiovascular disease." (PMID 33255278, 2020). "Chronic inflammation ultimately leads to insulin resistance and metabolic syndrome as a result of the uninterrupted cytokine release damaging the insulin-sensitive cells in liver, muscle and adipose tissue." (PMID 33304339, 2020). "To further identify the mechanism of CaMKIV on insulin resistance, we next analyzed the markers of ER stress, autophagy and insulin sensitivity after blockage mTOR/CREB signaling in Tun-treated adipocytes." (PMID 32660483, 2020). "In the liver, insulin inhibits the expression of key gluconeogenic enzymes; therefore, insulin resistance leads to elevated hepatic glucose production." (PMID 32971975, 2020). "The impact of insulin and insulin resistance on the operation of various organs/pathways is captured in accordance with published research." (PMID 32155149, 2020). "STZ is a naturally occurring alkylating agent which is extremely toxic to insulin-producing beta cells; two doses of STZ should thus result in insulin deficiency, whereas the high-fat diet results in insulin resistance." (PMID 33015095, 2020). "At the final period of the experiment (120 days), the insulin tolerance test was performed, and an increase in insulin resistance was observed in the DH group (10, 20, and 30 min) when compared to the control group." (PMID 32492810, 2020). "TNF-α and IL-6 can alter insulin sensitivity and stimulate the phosphorylation of serine residues instead of tyrosine in insulin receptor substrate-1 (IRS-1), thus inhibiting the activation of insulin signaling and sustaining insulin resistance." (PMID 32947869, 2020).
Insulin resistance (continued). "Hepatic insulin resistance leads to severely dysregulated glucose homeostasis and lipid over-accumulation, which would aggravate hepatic insulin insensitivity." (PMID 33240683, 2020). "The important metabolic effects of adiponectin, as well as the growing evidence regarding the role of adipocytokines in the regulation of insulin sensitivity during pregnancy, makes this hormone a putative regulator of insulin resistance during pregnancy." (PMID 32244842, 2020). "Their findings suggest that the selective increase in capillarization surrounding more insulin‐sensitive oxidative muscle fibers act to alleviate obesity‐related insulin resistance." (PMID 33038072, 2020). "Insulin tolerance tests and gene expression analysis showed that Ob-IR-/- mice had severe insulin resistance with significantly decreased pancreatic β-cell mass and insulin expression." (PMID 33537005, 2020). "The present study showed significant differences in fasting insulin levels and insulin resistance between NWO and NWNO women." (PMID 33198735, 2020). "It plays a vital role in the development of insulin resistance by reducing the expression of glucose transporter type 4 (GLUT 4) that regulates insulin." (PMID 32148647, 2020). "Our results also showed that fasting blood glucose, serum insulin concentrations, and insulin resistance in T2DM mice were improved after HIIT." (PMID 32922365, 2020). "Islet β‐cell function is a crucial determinant for the development of overt hyperglycemia, and it adapts to metabolic burden in the face of insulin resistance through increasing insulin secretion to maintain euglycemia (Boland, Rhodes, & Grimsby, 2017)." (PMID 32884732, 2020). "PBA treatment decreased the ratio insulin/body weight to a similar value as that of mice treated with LF diet, indicating that the chemical chaperone alleviates insulin resistance in obese mice." (PMID 32123584, 2020). "Treatment of 3T3-L1 adipocytes with iron sulfate promoted insulin resistance in vitro by limiting transcription of the insulin sensitizing adipokine, adiponectin." (PMID 33133674, 2020). "Rats exposed to a high-fat diet and administered 50 mg/kg CA for 20 weeks showed an increase in insulin secretion and an improvement in insulin resistance." (PMID 32566690, 2020). "Obesity-related chronic inflammation is one of the initiating factors of insulin resistance; hence blocking inflammation would improve insulin sensitivity." (PMID 32132984, 2020). "Correspondingly, M-LRP2−/− mice displayed insulin resistance, as evidenced by a blunted decrease in blood glucose levels after insulin injection over control mice." (PMID 32332780, 2020). "T2DM is a complex metabolic disorder characterized by progressively declined insulin action (insulin resistance) and consequent inability to compensate for insulin resistance due to insufficient beta cell function." (PMID 31900229, 2020). "The recorded high insulin levels in plasma and severe hyperglycemia in db/db mice undoubtedly indicate insulin resistance, which is consistent with the literature." (PMID 32340263, 2020). "To further explore the participation of liver α7nAChR in the development of insulin resistance, we investigated insulin-stimulated phosphorylation of AKT in HFD-fed KOα7Alb-Cre mice with deletion of α7nAChR in the hepatocytes." (PMID 31913329, 2020). "There were also significant effects of interactions between diagnosis and a history of ACEs on the levels of insulin (F = 4.497, p = 0.036) and homeostatic model assessment of insulin resistance (HOMA-IR) (F = 3.987, p = 0.048)." (PMID 33255883, 2020). "This disease is initiated by the worsening of pancreatic dysfunction, established when insulin production by β-pancreatic cells cannot keep up with the increase in peripheral insulin resistance." (PMID 32903730, 2020).
Insulin resistance (continued). "Adipose morphology was correlated with insulin resistance as estimated by fasting serum (fS)-Insulin (standardized beta 0.24, p 2 × 10−12), and HOMA-IR (standardized beta 0.16, p 1.5 × 10−6) after adjusting for age and sex." (PMID 32349335, 2020). "Although the mechanisms underlying the relationship between obesity and skeletal muscle insulin resistance remain controversial, the prevailing theory links insulin resistance to the increasing circulating free fatty acids (FFA)." (PMID 32438641, 2020). "For fasting insulin, as indices of insulin resistance in PCOS, women with CC genotype showed higher insulin levels, when compared to women with CT genotype." (PMID 33033446, 2020). "Excessive levels of selenoprotein P (SeP) have been shown in humans with metabolic diseases and are positively correlated with insulin resistance, which is consistent with its insulin-desensitizing effects observed in animal and in vitro models." (PMID 32604889, 2020). "In contrast, the prevalence of initial glycemic alterations (defined as “prediabetic conditions”) and more importantly, the number of patients showing peripheral resistance to insulin induced glucose caption (“insulin resistance” [IR]) is much higher." (PMID 33137934, 2020). "Studies from our department in primary astrocytes from TLR2/4 knock-out mice have shown increased phosphorylation of p-Akt and p-GSK after insulin stimulation and knockout animals were protected from brain insulin resistance on high-fat diet." (PMID 33047031, 2020). "Defects in insulin signaling impair glucose utilization and are believed to be a critical factor in insulin resistance pathogenesis." (PMID 32425738, 2020). "Treatment of insulin resistance is directed at increasing insulin sensitivity in peripheral tissues such as skeletal muscle and adipose tissue." (PMID 32290353, 2020). "After 12 weeks’ feed, the experimental group showed enhanced insulin secretion and reduced insulin resistance, as well as improved the gut microbiome dysbiosis." (PMID 33042976, 2020). "An obese and/or diabetic state can exacerbate these pregnancy-induced changes in maternal insulin levels as insulin resistance, hyperinsulinemia and low-grade inflammation are commonly seen in these states." (PMID 32494038, 2020). "Resistin (or “resistance to insulin”) was discovered in mice in 2001 as an adipocyte-derived signaling molecule, and named for its role in inducing insulin resistance." (PMID 33192583, 2020). "Improvement in insulin sensitivity in T2DM patients is an important aspect of treatment as insulin resistance is generally undiagnosed and the body compensates by secreting excess insulin to keep the blood glucose within the normal value." (PMID 32987623, 2020). "Skeletal muscle lipid composition is thought to play a role in the development of insulin resistance since abundant content of saturated fatty acids correlates with lower insulin sensitivity." (PMID 33171690, 2020). "The reported improvements in systemic insulin resistance, insulin signaling and glucose uptake in skeletal muscle by renin inhibition were associated with decreases in the levels of Ang II, aldosterone, AT1R, oxidative stress, and fibrosis." (PMID 32235782, 2020). "Since adipose tissue is one of the largest target organs of insulin, adipose insulin resistance because of visceral obesity contributes to systemic insulin resistance and consequent hyperinsulinemia." (PMID 33005239, 2020). "MTPα knockdown enhanced TNF-α-induced insulin resistance, as evidenced by significantly decreased insulin-stimulated glucose uptake in TNF-α-treated 3T3-L1 adipocytes (p < 0.0001)." (PMID 33009367, 2020). "The insulin resistance can hence be attributed to a decrease in insulin responsiveness and a decrease in insulin sensitivity." (PMID 32872233, 2020).
Insulin resistance (continued). "Based on levels of fasting glucose and insulin, the calculated homeostasis model assessment-estimated insulin resistance (HOMA-IR) index was lower after 5 weeks (−16.2%) and 10 weeks (−29.4%) in UA-treated mice than that of the vehicle group." (PMID 32218572, 2020). "Insulin resistance in this model also significantly impaired insulin-stimulated phosphorylation of PKB, SPEG and SERCA2a." (PMID 32367034, 2020). "Serum irisin levels, fasting blood glucose, serum insulin, homeostatic model assessment of the insulin resistance index (HOMA-IR), and β-cell function (HOMA-B2) were assessed." (PMID 32952453, 2020). "A less than expected response of target organs to insulin leads to a condition of insulin resistance with hyperinsulinemia for a compensatory increased insulin production by pancreatic β-cells." (PMID 31963572, 2020). "There were clinical studies which revealed insulin resistance improved after adrenalectomy in patients with phaeochromocytoma as well as those related to the improvement of insulin secretion." (PMID 33324347, 2020). "Some data in the literature show that Hp levels are directly correlated with obesity and insulin levels more than insulin resistance." (PMID 32695161, 2020). "For this they chose six parameters to inform the cluster, namely insulin resistance, insulin secretion, age at diagnosis of diabetes, body mass index (BMI), HbA1c and autoantibodies." (PMID 32785111, 2020). "Scientists have demonstrated that resveratrol improves glucose homeostasis, reduces insulin resistance, protects islet beta cells, improves insulin secretion, and improves metabolic disorders." (PMID 32420356, 2020). "The gold standard test to assess insulin resistance is the euglycemic–hyperinsulinemic clamp, which measures peripheral glucose uptake under conditions of elevated insulin concentrations." (PMID 32397662, 2020). "The results showed that KO mice had decreased insulin sensitivity (3.80 ± 0.11 mmol/L vs. 2.79 ± 0.10 mmol/L, P < 0.001), showing insulin resistance." (PMID 33060792, 2020). "Type 2 diabetes (T2D) is a progressive disease characterized by insulin resistance, defined as the inability of insulin to perform its functions at its target tissues, leading to an uncontrolled increase in blood glucose levels." (PMID 32718202, 2020). "Polyphenols have been extensively studied for their beneficial effects in metabolic syndrome and diabetes, as plant-based diet regimens rich in phenolic compounds have been shown to improve insulin secretion and insulin resistance." (PMID 33143088, 2020). "Probiotic consumption has also reduced the levels of high-sensitivity C-reactive protein, malondialdehyde, insulin, and insulin resistance and increased glutathione and insulin sensitivity, in comparison with the placebo." (PMID 33066156, 2020). "During a normal pregnancy, several changes in glucose and insulin metabolism lead to increased insulin resistance." (PMID 32664282, 2020). "The increase in placental hormones antagonizing the action of insulin in the second and third trimesters of pregnancy gives rise to a physiological increase in insulin resistance." (PMID 33335512, 2020). "Hyperglycemia, insulin resistance (IR), the disruption of insulin synthesis by β cells supports a state of chronic inflammation in T2D patients." (PMID 32517119, 2020). "The main elements of IST such as Akt, IRS, IRS-1, and GSK-3 are under the influence of free radicals that are downregulated by the oxidative stress thereby impairing insulin sensitivity leading to insulin resistance and DM." (PMID 32215179, 2020). "Our findings also revealed that treatment with 3% or 5% GEP significantly improved obesity and insulin resistance parameters, as well as the expression and activation of proteins related to insulin signaling pathways." (PMID 33142995, 2020). "If CSS model is appropriate, insulin resistance or altered insulin levels are bound to change fasting glucose levels." (PMID 33365205, 2020).